MMP2 (matrix metallopeptidase 2)
Diseases named in the same sentence as MMP2 in open-access papers (continued):
Sharing a sentence is not in itself a finding about the gene and the disease.
cervical carcinoma (continued). "MMP-2 gradually increases with the increasing grade of cervical intraepithelial neoplasia and reaches a maximum in cervical cancer." (PMID 36982551, 2023). "Elevated concentrations of MMP-2 and MMP-9 were correlated with the FIGO stage and are associated with poor prognosis in endometrial cancer, whereas in cervical cancer, elevated concentrations of MMP-9 have been associated with a better outcome." (PMID 36982551, 2023). "Hlegumain promoted cervical cancer invasion and metastasis through the degradation of extracellular matrix by activating MMP-2 and induced endothelial permeability and tumor metastasis by downregulating ZO-1." (PMID 36797792, 2023). "In the mechanism, the extracellular matrix is degraded and the basal membrane expression of cervical cancer cells is destroyed by up-regulating the expression of MMP-2 and MMP-9, thereby resulting in carcinogenesis and metastasis." (PMID 35445019, 2022). "And HK2 also promoted cell motility and distant metastasis by elevating fibronectin/MMP2/MMP9 in cervical cancer cells." (PMID 35953860, 2022). "In cervical cancer (CC) an upregulated MMP-2 and TIMP-2 levels in the stroma are related to a decrease in patient survivability." (PMID 34912809, 2021). "Treatment with cisplatin or quercetin alone did not reduce the expression of MMP2 protein in cervical cancer cells but their combination significantly decreased MMP2 expression, which inhibited the migration and invasion of cervical cancer cells." (PMID 34680171, 2021). "RIPK4 promoted invasion and metastasis of cervical cancer cells by inhibiting expression of 'vimentin, MMP2 and fibronectin which were pivotal molecules of epithelial-mesenchymal transition process." (PMID 33487072, 2021). "Compared to the control group, we found that epithelial marker E‐cadherin was up‐regulated in the si‐HSDL2 groups, while mesenchymal markers (Vimentin, Snail, Slug and MMP‐2) were considerably down‐regulated in all three cervical cancer cell lines." (PMID 33738911, 2021). "In conclusion, high expression levels of MMP-2 and TIMP-2 in the stroma are significantly associated with poor survival in cervical cancer patients." (PMID 32669083, 2020). "Here, we confirmed that cervical cancer cells upregulated the expression of MMP2, MMP9, and MMP12 of SCs." (PMID 32064233, 2020). "TAO has also been shown to inhibit the phosphorylation of Akt, an upstream signaling protein in MMP-2 and 9 expressions in both cervical cancer cell lines and HUVECs." (PMID 33086573, 2020). "High expression levels of MMP-2 and TIMP-2 in the stroma were significantly associated with poor survival in cervical cancer patients." (PMID 32669083, 2020). "PA inhibits human cervical cancer cell growth and invasion by suppressing MMP-2 expression and ERK1/2 pathway activation." (PMID 32244796, 2020). "We also demonstrated that up‐regulation of C16orf74 can rescue the inhibitory role HAND2‐AS1 overexpression has on cervical cancer cell proliferation, migration and invasion, as evidenced by promoted expression of N‐cadherin, vimentin, MMP‐2 and MMP‐9." (PMID 32314545, 2020). "We investigated the plasma levels and diagnostic power (ROC curve analysis) of M-CSF, MMP-2, TIMP-2 and tumor markers CA 125 and SCC-Ag in cervical cancer (CC) patients as compared to control group." (PMID 30820752, 2020). "WB assays showed that the expression levels of MMP-2 and MMP-9 proteins were significantly reduced, indicating that UBE2R2-AS1 inhibits the invasion and the migration of cervical cancer cells by regulating MMP-2/9 expression." (PMID 33336075, 2020). "In conclusion, we demonstrated that GPNMB contributed to the tumorigenesis of cervical cancer, at least in part, by regulating MMP-2/MMP-9 activity in tumor cells via activation of canonical Wnt/β-catenin signaling." (PMID 30484490, 2018). "Our findings are in line with our previous studies showing that KP suppressed MMP-2 production in cervical cancer, HeLa cells." (PMID 29891015, 2018).
cervical carcinoma (continued). "Our findings indicate that the proinvasive activity of SEMA5A is associated with the induction of MMP-2 and MMP-9 in HeLa cervical cancer cells." (PMID 29977159, 2018). "The FR3 is also considered promising because it inhibits MMP-2 and MMP-9, enzymes that are closely linked to dissemination of a type of cancer considered highly invasive and highly expressed in cervical cancer." (PMID 29770331, 2018). "Our results showed that inhibition of CCL19 inhibited expression of MMP-9 and MMP-2, suggesting that CCL19 increase the aggressiveness of cervical cancer cells, possibly by regulation of MMP-2 and MMP-9." (PMID 29088748, 2017). "Recent evidence has suggested that the positive expression of matrix metalloproteinase-2 (MMP-2) and matrix metalloproteinase-9 (MMP-9) was associated with PTX3 expression in the regulation of human cervical cancer cell metastasis." (PMID 28489600, 2017). "The anti-viral drugs ribavirin and indinavir appear to protect against HPV-18-induced cervical cancer by decreasing the secretion of MMP-2 and MMP-9." (PMID 29267213, 2017). "In our experiments, the protein expression of MMP-2 was dramatically reduced in cervical cancer cells with SLC39A7 knockdown, probably as a result of overexpression of E-cadherin, thus promoted the invasion and metastasis of these cells." (PMID 29285013, 2017). "Human papillomavirus (HPV) 16-E6 and -E7 are oncoproteins that together promote cervical cancer invasiveness by specifically increasing MMP-2 transcription." (PMID 29267213, 2017). "MZF1 inhibits the migratory and invasive capability of cervical cancer cells through reducing MMP-2 expression." (PMID 27259238, 2016). "To further explore the underlying mechanism of RIPK4 in promoting the migration and invasion of cervical cancer cells, we measured Vimentin, MMP2 and Fibronectin mRNA expression in RIPK4-siRNA-transfected cells and control cells." (PMID 26148476, 2015). "Knockdown of RIPK4 reduced cell migration and invasion via inhibition of Vimentin, MMP2 and Fibronectin expression in cervical cancer cells." (PMID 26148476, 2015). "Further studies revealed that suppression of RIPK4 expression significantly inhibited Vimentin, MMP2 and Fibronectin expression in two cervical cancer cell lines." (PMID 26148476, 2015). "For instance, the upregulation of MMP-2 and MMP-9 collagenases is associated with the invasion and metastasis of cervical uterine neoplasm." (PMID 24804928, 2014). "MMP-2 is also an important factor in the invasion of cervical cancer through degradation of the extracellular matrix." (PMID 24011340, 2013). "Although overexpression of several types of MMP has been observed in cervical cancer tissues, only increased levels of MMP-2 and MMP-9 were shown to correlate with poor prognosis in patients." (PMID 23967226, 2013). "In conclusion, our study demonstrated that HPV16E6 and E7 oncoproteins cooperate in promoting cervical cancer invasiveness by specifically upregulating MMP-2 and MT1-MMP transcription in a similar manner." (PMID 23967226, 2013). "The data suggest that Ficus reduced the migration as well as invasion of cervical cancer cells by modulating the expression of Her-2 and MMP-2 proteins." (PMID 23922932, 2013). "Based on this, we hypothesize that Oct4 might promote cervical cancer malignant behavior via regulating MMP2 and 9 and activating the p38 signaling pathway." (PMID 38430256, 2024). "Although the presence of Th17 cells in situ was linked with cervical cancer progression, and IL‐17A was found to upregulate MMP‐2 and MMP‐9 expression favoring migration of cervical cancer cell lines, Th17‐induced mechanisms underlying cervical cancer metastases are not reported so far." (PMID 37899663, 2024). "Additionally, studies on SiHa and HeLa cervical cancer cells have shown that ALA and n-3 fatty acids regulate the growth of cervical cancer cells by reducing cell migration with a concomitant reduction in the expression of MMP-2, MMP-9, and VEGF." (PMID 37761033, 2023).
cervical carcinoma (continued). "Moreover, both the high expression of MMP-2 and low MMP-9 expression in both tumor and stroma cells seem to be associated with poor prognosis in cervical cancer, as well as in several tumors." (PMID 37509428, 2023). "Furthermore, MNBE inhibited the migration of cervical cancer cells accompanied by modulation of migration-related genes, including zona occludens-1 (ZO-1), matrix metalloproteinase 2 (MMP2), focal adhesion kinase (FAK), N-cadherin, snail, and E-cadherin." (PMID 36088372, 2022). "To investigate if Sdc-1 in its different forms influences the expression of invasion-related factors, we analyzed the expression levels of E-cad, MMP2, and tissue inhibitor of metalloproteinases 1 (TIMP-1), which are also associated with the metastasis of cervical cancer cells by qRT-PCR." (PMID 35155241, 2022). "With chemotherapy, quercetin potentiates the effect of cisplatin in cervical cancer cells due to the induction of apoptosis as a result of declining Matrix Metallopeptidase 2 (MMP2), Methyltransferase 3, N6-Adenosine-Methyltransferase Complex Catalytic Subunit (METTL3), P-Gp and ezrin production." (PMID 36080219, 2022). "Collectively, the data suggested that the inhibitory effect of MNBE on the migration of cervical cancer cells was at least partially associated with the inhibition of EMT via upregulating tight junction protein ZO-1 and downregulating the expression of MMP2, FAK, and N-cadherin gene transcripts." (PMID 36088372, 2022). "Co-treatment with quercetin and cisplatin synergistically inhibits proliferation, migration, and invasion and enhances apoptosis in HeLa and SiHa human cervical cancer cells by weakening matrix metallopeptidase 2 (MMP2), ezrin, P-glycoprotein, and methyltransferase-like 3 (METTL3) expressions." (PMID 36430891, 2022). "Similarly, the down-regulation of FABP5 in cervical cancer inhibits the in vivo and in vitro expression of MMP-2 and MMP-9." (PMID 35445019, 2022). "However, inhibition of PLAU expression has been shown to prevent the migration and invasion of cervical cancer cells through the downregulation of MMP2." (PMID 34702271, 2021). "Evidence has shown that STK39 could promote cervical cancer progression via the NF-κB/p38 MAPK/MMP2 pathway." (PMID 34604044, 2021). "A recent study demonstrated that PLAU1 knockdown reduced the migration and invasion abilities of cervical cancer cells by downregulating MMP2 expression, which confirmed that PLAU1 influences the biological activities of malignant tumors via the regulation of MMPs." (PMID 33816223, 2021). "In addition, baicalin can also inhibit the migration and invasion of cervical cancer HeLa cells by downregulating the expression levels of MMP2 and MMP9 through the p38-MAPK pathway and has a concentration-dependent effect to a certain extent." (PMID 34421596, 2021). "This study aimed to assess whether the expression of MMP-2, MMP-9, MMP-14, TIMP-1, and TIMP-2 in tumors and in the adjacent stroma is associated with cervical cancer prognosis." (PMID 32669083, 2020). "APS can significantly inhibit the metastasis of C33A cells in cervical cancer, which may be achieved by reducing the levels of matrix metalloproteinase 2 (MMP2)." (PMID 32265719, 2020). "In addition, a previous study has shown that cell invasion is promoted via VEGF and MMP2 in cervical cancer." (PMID 31138113, 2019). "It was reported that the activation of MMP-2 in cervical cancer tissue could be mediated by a functional complex consisting of α(v)β3 integrin/membrane type-1 metalloproteinase-2 (MT1-MMP)/tissue inhibitor of metalloproteinase-2 (TIMP-2) on tumor cell surface." (PMID 30484490, 2018). "It would be very interesting to clarify whether there are possible associations among GPNMB, MMP-2/MMP-9, and HPV oncogenes, and whether GPNMB plays a role in HPV-negative cervical cancer cells in future study (26, –28)." (PMID 30484490, 2018).
cervical carcinoma (continued). "Furthermore, we found that GPNMB accelerated the tumorigenesis of cervical cancer in vitro by regulating MMP-2/MMP-9 activity via the Wnt/β-catenin pathway." (PMID 30484490, 2018). "Thereby highlighting a possible relationship between the NaV1.6 channels activity, the up regulation of the NHE-1 and the enhanced activity of MMP-2, that could lead to the observed increase in cell invasion of cervical cancer cells." (PMID 30158710, 2018). "In cervical cancer, dysregulation of MMP-2 and MMP-9 has been widely reported." (PMID 30484490, 2018). "In contrast, high-grade lesions and invasive carcinomas showed high MMP-2 expression, suggesting that MMP-2 may constitute an early marker for cervical cancer progression." (PMID 30208169, 2018). "The invasive capacity of cervical cancer cells associated to NaV1.6 channels activity is mediated by a mechanism that involves the participation of NHE-1 and the specific secretion and proteolytic activity of MMP-2." (PMID 30158710, 2018). "Down-regulation of FZD7 in cervical cancer cells could inhibit cell invasion and migration by inhibiting the expression level and activities of MMP2 and MMP9, as well as inhibiting the expression of phosphorylated JNK and c-jun." (PMID 29029485, 2017). "Our current study reporting that KP extract can effectively reduce MMP-2 activity provides valuable information to support that KP may inhibit migration and invasion of cervical cancer cells." (PMID 28955234, 2017). "We supposed that SLC39A7 may indirectly regulate MMP-2 by altering E-cadherin expression in cervical cancer." (PMID 29285013, 2017). "Furthermore, knockdown of PTX3 significantly decreased the potential of migration and invasion of cervical cancer cells by inhibiting matrix metalloproteidase-2 (MMP-2), MMP-9, and urokinase plasminogen activator (uPA)." (PMID 27377307, 2016). "IL-17A could promote the migration and invasion of cervical cancer cell via up-regulating MMP2 and MMP9 expression, and down-regulating TIMP-1 and TIMP-2 expression via p38/NF-κB signal pathway." (PMID 25250801, 2014). "Moreover, FRaq reduced the migration as well as invasion capability of both the cervical cancer cell lines accompanied with downregulation of MMP-2 and Her-2 expression." (PMID 23922932, 2013). "In addition, a relationship between MMP-2 mRNA levels and cervical cancer invasiveness has been demonstrated." (PMID 23967226, 2013). "Interestingly, MMP9 and MMP2 up-regulation in cervical cancer was previously reported and the combined overexpression of MMP9, MMP11 and TIMP1 has been associated with the invasive features of some cancers." (PMID 15989693, 2005). "Taken together, the results obtained have suggested that the MALAT-ALKBH5 signaling axis may be activated in HPV-positive cervical cancer cells, which could contribute to cell proliferation and metastasis through the regulation of key genes, such as MMP2 or MMP9." (PMID 37639643, 2023). "In addition, APS significantly inhibited the migration and invasion abilities of cervical cancer C-4I cells; this effect may be related to the upregulation of E-cadherin expression and inhibition of MMP2 activity." (PMID 32265719, 2020). "The differential effect between cervical cancer cell lines and esophageal squamous cell lines could be a reflection of the cellular context of the gene environment, highlighting that MMP2 and MMP9 are downregulated by several miRNAs, independent of UTR binding sites." (PMID 30696040, 2019). "In addition, MMP-2 and MMP-9 expression are associated with the progression of cervical cancer when exposed to low concentrations of arsenic trioxide and humic acid, and both of these proteins play important roles in cancer progression and remodeling of the ectocervix." (PMID 29267213, 2017). "Interestingly, Ficus significantly reduced the expression of both HER-2 and MMP-2 that might have resulted in the observed decrease in the migration as well as invasion of cervical cancer cells." (PMID 23922932, 2013).